UFSP1 (UFM1 specific peptidase 1)
Description:
Thiol-dependent isopeptidase that specifically mediate the processing of UFM1 precursors as well as the deconjugation of UFM1 from target proteins. Mainly responsible for the maturation of the UFM1 precursor, a prerequisite for conjugation reactions.
Synonyms: UFSP
Tractability: No criterion of Open Targets' tractability assessment is met for any kind of drug.
Gene: Protein-coding gene on chromosome 7 (100,888,721 to 100,889,715, reverse strand). Ensembl gene ENSG00000176125.
Subcellular location: Cytoplasm, cytosol
Gene Ontology:
Molecular function: cysteine-type peptidase activity; deUFMylase activity; protein binding
Biological process: protein maturation; protein ufmylation
Cellular component: cytosol
Genetic constraint (gnomAD): Loss-of-function variants: 2 observed, 1.27 expected, observed/expected ratio (o/e) 1.57, 90% interval 0.47 to 1.93. That is too few expected variants to judge how well the gene tolerates losing a copy. Missense variants: 261 observed, 187.02 expected, observed/expected ratio (o/e) 1.4, 90% interval 1.26 to 1.55. Synonymous variants: 119 observed, 78.01 expected, observed/expected ratio (o/e) 1.53, 90% interval 1.31 to 1.77.
Homologues: Orthologues: guinea pig UFSP1 (82% identical), mouse Ufsp1 (76% identical), rat Ufsp1 (72% identical), chimpanzee UFSP1 (64% identical), pig UFSP1 (56% identical), zebrafish ufsp1 (44% identical), Drosophila melanogaster Ufsp1 (36% identical). Paralogues in human: UFSP2 (36% identical).
Diseases named in the same sentence as UFSP1 in open-access papers:
UFSP1 is named in the same sentence as 4 diseases in open-access papers, as found by Europe PMC text mining. Sharing a sentence is not in itself a finding about the gene and the disease. The quoted sentences say what the papers report.
cancer (1 paper, 2023). A tumor composed of atypical neoplastic, often pleomorphic cells that invade other tissues. "A comprehensive analysis of genomic alterations in the eight UFMylation family genes (UFM1, UBA5, UFC1, UFL1, UfBP1, CDK5RAP3, UfSP1, and UfSP2) across the TCGA database of 33 cancer types identified 55 recurrent and focal somatic copy number alteration events in UFMylation family genes." (PMID 37947621, 2023).
infection (1 paper, 2025). The state of being infected such as from the introduction of a foreign agent such as serum, vaccine, antigenic substance or organism. "Additionally, given that that UFMylation is regulated by stress cues such as DNA damage, infection, and ER stress, it would be intriguing to investigate whether the role of Ufsp1 becomes apparent under pathological or challenged conditions, for instance ageing and exercise, in future studies." (PMID 40748989, 2025).
UFSP1 also shares sentences with these, for which no sentence is quoted: congenital myasthenic syndrome (1 paper); viral infection (1).